ZSWIM1 (zinc finger SWIM-type containing 1)
Synonyms: C20orf162; dJ337O18.5
Tractability: Antibody: the Human Protein Atlas places it where antibodies can reach. PROTAC: ubiquitination databases record sites on it.
Gene: Protein-coding gene on chromosome 20 (45,881,227 to 45,885,266, forward strand). Ensembl gene ENSG00000168612.
Subcellular location (Human Protein Atlas): Cytosol; Plasma membrane
Gene Ontology:
Molecular function: zinc ion binding
Cellular component: nucleus
Genetic constraint (gnomAD): Loss-of-function variants: 23 observed, 31.01 expected, observed/expected ratio (o/e) 0.74, 90% interval 0.53 to 1.05. The upper end of that interval is the gene's LOEUF score, 1.05, which puts it in group 4 of 6, group 1 being the genes least tolerant of losing a copy. Missense variants: 511 observed, 629.95 expected, observed/expected ratio (o/e) 0.81, 90% interval 0.75 to 0.87. Synonymous variants: 228 observed, 254.23 expected, observed/expected ratio (o/e) 0.9, 90% interval 0.8 to 1.
Homologues: Orthologues: chimpanzee ZSWIM1 (99% identical), macaque ZSWIM1 (92% identical), dog ZSWIM1 (82% identical), pig ZSWIM1 (80% identical), mouse Zswim1 (80% identical), rabbit ZSWIM1 (79% identical), rat Zswim1 (79% identical), guinea pig ZSWIM1 (76% identical), tropical clawed frog zswim1 (35% identical). Paralogues in human: ZSWIM3 (27% identical).
Diseases named in the same sentence as ZSWIM1 in open-access papers:
ZSWIM1 is named in the same sentence as 6 diseases in open-access papers, as found by Europe PMC text mining. Sharing a sentence is not in itself a finding about the gene and the disease. The quoted sentences say what the papers report.
ovarian carcinoma (2 papers, 2022 to 2023). A malignant neoplasm originating from the surface ovarian epithelium. "By regulating T helper cells development, ZSWIM1 plays a critical role in immune system, and signals a poor prognosis of ovarian cancer." (PMID 37143087, 2023).
lung adenocarcinoma (1 paper, 2024). A carcinoma that arises from the lung and is characterized by the presence of malignant glandular epithelial cells. "Overexpression of TRIM21 reduced the promoting effect of ZSWIM1 on the proliferation, migration, and invasion of lung adenocarcinoma cells, and reversed the impact of ZSWIM1 on the expression of E-cadherin and Vimentin." (PMID 38880921, 2024).
tumor (3 papers, 2021 to 2022). "`The activation sensitive nature of ZSWIM1 expression shows that it plays a novel role in the development or function of T helper cells, which primarily mediate anti-tumour immunity." (PMID 35057823, 2022). "The results showed that the expression levels of CORO1B, GOLGA7, PCSK4, ST6GALNAC4, and ZSWIM1 in normal tissues were significantly higher than those in tumor tissues, which were similar to the trends detected in the TCGA dataset." (PMID 34970268, 2021).
ZSWIM1 also shares sentences with these, for which no sentence is quoted: cancer (3 papers); hepatocellular carcinoma (1); schizophrenia (1).